IGLV5-45 (immunoglobulin lambda variable 5-45)
Description:
V region of the variable domain of immunoglobulin light chains that participates in the antigen recognition. Immunoglobulins, also known as antibodies, are membrane-bound or secreted glycoproteins produced by B lymphocytes. In the recognition phase of humoral immunity, the membrane-bound immunoglobulins serve as receptors which, upon binding of a specific antigen, trigger the clonal expansion and differentiation of B lymphocytes into immunoglobulins-secreting plasma cells. Secreted immunoglobulins mediate the effector phase of humoral immunity, which results in the elimination of bound antigens. The antigen binding site is formed by the variable domain of one heavy chain, together with that of its associated light chain. Thus, each immunoglobulin has two antigen binding sites with remarkable affinity for a particular antigen. The variable domains are assembled by a process called V-(D)-J rearrangement and can then be subjected to somatic hypermutations which, after exposure to antigen and selection, allow affinity maturation for a particular antigen.
Synonyms: IGLV545; V4-2
Gene: Immunoglobulin variable (V) gene on chromosome 22 (22,375,986 to 22,376,505, forward strand). Ensembl gene ENSG00000211650.
Subcellular location: Secreted; Cell membrane
Gene Ontology:
Biological process: immune response
Cellular component: extracellular region; immunoglobulin complex; plasma membrane
Homologues: Paralogues in human: IGLV5-37 (86% identical), IGLV5-48 (76% identical), IGLV5-52 (76% identical), IGLV11-55 (66% identical), IGLV4-60 (56% identical), IGLV4-69 (54% identical), IGLV1-40 (52% identical), IGLV1-50 (51% identical), IGLV2-18 (51% identical), IGLV1-44 (50% identical), IGLV1-47 (50% identical), IGLV2-11 (50% identical), and 81 more.
Diseases named in the same sentence as IGLV5-45 in open-access papers:
IGLV5-45 is named in the same sentence as 1 disease in open-access papers, as found by Europe PMC text mining. Sharing a sentence is not in itself a finding about the gene and the disease.
IGLV5-45 shares sentences with these, for which no sentence is quoted: infection (1 paper).